CRP (C-reactive protein)
Diseases named in the same sentence as CRP in open-access papers (continued):
Sharing a sentence is not in itself a finding about the gene and the disease.
COVID-19 (continued). "Moreover, we compared the performance of our nomogram in predicting the survival probability of COVID-19 with other models reported in the literature (Cai’s model: age, D-dimer, CRP; Cheng’s model: UREA, age, D-dimer)." (PMID 36389149, 2022). "COVID-19 patients with higher serum CRP are prone to evolve to severe disease states." (PMID 35204599, 2022). "Interestingly, aCL and aPS/PT from COVID-19 patients strongly correlated with markers of endothelial cell activation and modestly with those of NETs/thrombo-inflammation including C-reactive protein, D-dimer and calprotectin." (PMID 35812410, 2022). "Therefore, our study evaluated the use of PTX3 blood concentration as a potential marker of COVID-19 severity and compared its performance with those of CRP and of other routinely determined laboratory inflammation markers." (PMID 35464745, 2022). "Moreover, increased laboratory infection parameters (e.g., leukocyte count, CRP and ferritin) have been reported to be useful as predictive biomarkers for disease severity and overall COVID-19 prognosis." (PMID 36548347, 2022). "These function in inflammation (e.g. C-reactive protein), coagulation and vascular dysfunction (e.g. von Willebrand factor), complement cascade (e.g. Complement C1q subcomponent subunit C), and other biological processes altered by COVID-19 (e.g. Cystatin C)." (PMID 35702332, 2022). "In COVID-19, IL-6 and CRP showed the highest prognostic value in the univariable model." (PMID 35622838, 2022). "Taken together, these findings suggest that multi-parameter analysis of pGSN, cytokines and antibodies could predict COVID-19 hospitalization outcomes with greater certainty compared with conventional clinical laboratory markers such as CRP and ferritin." (PMID 36148234, 2022). "Moreover, IL-6 level in saliva of COVID-19 patients was positively correlated with serum ferritin (P < 0.0001), and had a positive trend with D-dimer and CRP." (PMID 36163397, 2022). "Furthermore, COVID-19 leads to elevated inflammatory markers, such as C-reactive protein (CRP), interleukin-6, and tumor necrosis factor alpha (TNF-α)." (PMID 35588115, 2022). "We also analyzed whether several biomarkers of the inflammatory response or tissue damage such as the plasma levels of CRP, ferritin, LDH or D-dimers, also associated to severity of COVID-19 were correlated with TL." (PMID 35996190, 2022). "Their results showed that vitamin D levels were inversely correlated with the markers used for monitoring the condition of COVID-19 patients: ferritin, CRP, and D-dimer, and serum vitamin D was low in symptomatic patients and normal in non-symptomatic patients." (PMID 35754946, 2022). "Additionally, elevated levels of IL-17 were found to increase C-reactive protein, which was upregulated in COVID-19 severe cases and plays a crucial role during infection as an early defense innate immune system." (PMID 35955801, 2022). "Overall, the published data suggesting that in the early stages of COVID-19, CRP levels may reflect disease severity, are in line with our findings." (PMID 35603207, 2022). "Persistently high WBC, CRP and neutrophil levels and low lymphocyte levels could be considered to be valuable indicators of mortality among COVID-19 patients treated with tocilizumab." (PMID 35858016, 2022). "Additionally, serum CRP levels have been used to monitor COVID-19 progression and patients’ response to COVID-19 treatments, such as tocilizumab." (PMID 36089575, 2022). "In a retrospective analysis of 103 children with COVID-19, inflammatory markers (C-reactive protein, procalcitonin, fibrinogen, D-dimer) were significantly elevated in children with moderate to severe clinical signs, while serum 25(OH)D level was significantly lower." (PMID 35601441, 2022).
COVID-19 (continued). "Multiple studies have shown that the clinical course of critically ill COVID-19 patients is associated with elevated levels of routine laboratory parameters such as WBC, creatinine, C-reactive protein, procalcitonin, as well as with lymphopenia and thrombocytopenia." (PMID 35563870, 2022). "This could be explained by interleukin-6 (IL-6) which is a sensitive indicator in inflammatory conditions as it induces the synthesis of CRP during inflammation, and it was significantly higher in severe COVID-19 cases." (PMID 36064554, 2022). "This may reflect an effect of a downgraded inflammatory response after administration of dexamethasone, an assumption supported by the fact that maximal CRP was significantly lower in dexamethasone-treated ICU patients with COVID-19." (PMID 36359231, 2022). "In addition to IL-6, CRP at diagnosis showed a good predictive ability of death in CHD patients with COVID-19 (the best cut-off value of 7.4 mg/dL, sensitivity of 87%, and specificity of 94%) (AUC: 0.9306; 95%CI: 0.8175–1.000; p = 0.006)." (PMID 36422198, 2022). "This study also revealed that serum H2S level was negatively correlated with the level of C-reactive protein (CRP) and IL-6 considered as the main and relevant parameter in predicting the most severe course of respiratory failure, lung injury and death in COVID-19." (PMID 36039860, 2022). "Combining troponin I, D-dimer and C-reactive protein levels with automated quantitative chest computed tomography (CT) data has not been previously evaluated for risk stratification in COVID-19." (PMID 35176874, 2022). "The combination of NLR and CRP may serve as a valuable early marker to assess the prognosis and evaluate the severity of clinical symptoms among COVID-19 patients." (PMID 36457636, 2022). "Several inflammation-associated markers such as C-reactive protein (CRP), ferritin, fibrinogen, D-dimer, neutrophil levels, urea in blood, and the cytokines IL-6, IL-10, and TNF-α have being associated with COVID-19 progression and play an important role in the development of acute lung injury." (PMID 36203752, 2022). "CXCL8, along with IL-37 and CRP, could be combined into a highly sensitive model to effectively differentiate severe cases from moderate ones in the COVID-19 population." (PMID 35037831, 2022). "When considering the COVID-19-related variables, we see that the participants for whom the final outcome was recorded had significantly higher values for CRP (108.9 [96.5] mg/L vs. 70.6 [70.3] mg/L; p < 0.001) and lower values for SA (3.5 [0.6] g/dL vs. 3.8 [0.5] g/dL; p < 0.001)." (PMID 35740416, 2022). "The most diagnostically significant marker of the severity of COVID-19 is C-reactive protein." (PMID 35603207, 2022). "The best test performance for differentiating bacterial/fungal secondary infections and COVID-19 and/or ECMO associated inflammation was achieved by IL-10 (ROC-AUC 0.84) and a multivariant step-wise regression model including CRP, IL-6, PCT, and IL-10 (ROC-AUC 0.93)." (PMID 36275812, 2022). "We conducted a prespecified subgroup analysis by sex based on earlier work showing that metformin lowers CRP more in women than men, improved cancer mortality in women but not men, and conveyed greater protection against severe outcomes from COVID-19 in women compared to men." (PMID 36395143, 2022). "Similarly, IL-6 and CRP ranged among the strongest predictors for ICU admission or death at 30 days in COVID-19 (AUC for IL-6 0.794 [95%CI 0.694–0.894]; AUC for CRP 0.807 [95%CI 0.721–0.893]) and both controls." (PMID 35622838, 2022). "ESR and CRP are much higher in dead patients with COVID-19 than in the other groups (p < 0.001)." (PMID 36570594, 2022). "Furthermore,a report released recently by a Chinese team discovered that three important indicators (LDH, CRP, and lymphocyte) can be used to predict COVID-19 mortality with over 90% of accuracy." (PMID 35013702, 2022).
COVID-19 (continued). "However, more adherence to unhealthy or traditional dietary patterns was associated with higher CRP and ESR, risk of severe COVID-19, and hospitalization duration." (PMID 36082030, 2022). "The newly published Consensus Statement from the International COVID-19 Thrombosis Biomarkers Colloquium establishes elevated levels of CRP, D-dimers and reduced platelet count are significantly associated with in-hospital mortality, which supports our own data." (PMID 36078933, 2022). "It is widely thought that the LDH concentration is a useful marker in evaluating the prognosis of different types of pneumonia, such as pneumocystis jiroveci pneumonia and community-acquired pneumonia, and a significant correlation between LDH and CRP in COVID-19 has been documented." (PMID 36389149, 2022). "On the other hand, it is believed that LDH and CRP may be related to respiratory function and serve as a predictor of respiratory failure in COVID-19 patients." (PMID 36291697, 2022). "CRP was used early on during the pandemic as a marker for the severity and progression of the disease in patients, as it increases dramatically together with IL-6 during the clinical manifestation of COVID-19." (PMID 35407379, 2022). "Among the clinical features evaluated in the present study that have been used as biomarkers for COVID-19, we could observe that ACE2 genetic variant had an impact on D-dimer, ferritin, lactate dehydrogenase, and CRP levels." (PMID 35250987, 2022). "We found a positive correlation between serum CRP level and the severity of COVID-19 (p = 0.03)." (PMID 35676519, 2022). "The inflammatory biomarker, CRP, was higher in deceased patients than in survivors, providing evidence for the presence of a cytokine storm that can contribute to the fatal outcome of many COVID-19 patients." (PMID 35053983, 2022). "Also, depressive symptoms are associated with increased levels of proinflammatory cytokines, C-reactive protein, leukocytes and neutrophil-to-lymphocyte ratio in COVID-19 patients and beyond, suggesting an increased prevalence of low-grade inflammation." (PMID 35331365, 2022). "Indeed, we observed a differential inflammation status among COVID-19 patients as also exemplified by significant differences in the levels of IL-6 and CRP." (PMID 36377893, 2022). "Several clinical or biological markers, including ferritin, C-reactive protein, and pro-inflammatory interleukin-1 and interleukin-6, have currently been identified to help predict the course of COVID-19 and, therefore, can potentially help to guide IGAM usage." (PMID 35799196, 2022). "Additionally, we analyzed the differences between the COVID-19 group and the healthy children according to the cutoff values for CRP, AST and LDH." (PMID 35976368, 2022). "Platelet-to-CRP ratio could act as an effective model in recognizing severe COVID-19 and multi-organ injuries." (PMID 35592303, 2022). "According to previous meta-analysis studies, the combination of traditional Chinese herbal medicine with conventional therapy was effective and safe in the treatment of mild to moderate COVID-19, which improved lung CT parameters, CRP, and clinical symptoms (fever, cough, and fatigue)." (PMID 35369061, 2022). "D1 of COVID-19 group: COHb levels were statistically significantly positively correlated with C-reactive protein CRP values (p = 0.003, r = 0.407) and with PCT values (p = 0.022, r = 0.324) and statistically significantly negatively correlated with serum lactate values (p = 0.038, r = −0.285)." (PMID 35208760, 2022). "In our study, while CRP, D-dimer, fibrinogen, and ferritin were found to be associated with disease severity in the univariate analysis; NLR and CRP were the only routine clinical laboratory parameters determined as independent variates for COVID-19 severity in the multivariate analysis." (PMID 36627978, 2022).
COVID-19 (continued). "Furthermore, the severity of inflammation (assessed as the leukocyte count, CRP, erythrocyte sedimentation rate and procalcitonin levels) and hypoxaemia have also been confirmed to be related to incident AF in COVID-19 patients." (PMID 36009487, 2022). "In the present study, positive CRP was more prevalent among COVID-19 outpatients than in controls." (PMID 35453291, 2022). "The course of COVID-19 includes the inflammatory cytokine storm, acute respiratory distress, and multiorgan failure with elevated levels of IL-6, D-dimer, serum ferritin, and C-reactive protein (CRP)." (PMID 36359290, 2022). "Similarly, a retrospective study showed that maximal CRP and ferritin levels during hospitalization were higher in obese than normal-weight COVID-19 patients." (PMID 35449994, 2022). "Studies found that CRP levels correlate with PCT levels among COVID-19 patients." (PMID 36295550, 2022). "In our study group, kidney disease, diabetes, and age were independently associated with fatality while, platelets, CRP, WBC, SGOT and high levels of serum creatinine biomarker of kidney injury, were also associated with fatality among COVID-19 hospitalized hypertensive patients." (PMID 36260598, 2022). "In this context, high sST-2 levels appear to correlate with serum levels of C-reactive protein (CRP), a classical marker of inflammation, with severe disease course and requirement for intensive care of COVID-19 patients, as well as with COVID-19-associated mortality." (PMID 36359409, 2022). "Tocilizumab, a kind of antibody that targeted the IL-6 signaling pathway, was demonstrated to be effective in treating severe COVID-19 patients, and biomarkers including C-reactive protein, procalcitonin, D-dimer, and lymphocyte levels were decreased after receiving tocilizumab administration." (PMID 35540724, 2022). "Data is limited on optimal co-infection testing strategies in COVID-19 and the utility of biomarkers such as C-reactive protein (CRP), white blood cell count (WBC), procalcitonin and neutrophil–lymphocyte ratio (NLR) to identify bacterial co-infections is conflicting." (PMID 35100984, 2022). "In addition, several biomarkers of frailty and aging have also been found to be related to COVID-19 progress, including elevated C-reactive protein, interleukin-6, lactate dehydrogenase, cortisol, and low vitamin D levels." (PMID 36244048, 2022). "In addition, in a published study in the USA, almost all hospitalized patients with COVID-19 had raised CRP levels." (PMID 35740195, 2022). "The specific thresholds that were considered for CRP and D-dimer were above the upper reference limit, and may perform differently in other populations with COVID-19." (PMID 35176874, 2022). "Some hematological parameters, including white blood cell (WBC), lymphopenia, C-reactive protein (CRP), and some biochemical parameters, such as lactate dehydrogenase (LDH), creatine kinase (CK), and troponin, were reported to be associated with COVID-19 severity." (PMID 36762324, 2022). "The serum ATX levels were reduced in all patients with COVID-19, irrespective of the disease severity, and were negatively associated with the serum CRP, D-dimer, and anti-severe acute respiratory syndrome coronavirus 2 (SARS-CoV-2) antibody levels." (PMID 36369824, 2022). "C-reactive protein levels were significantly higher in MP group than in COVID-19 group (p < 0.05)." (PMID 35125096, 2022). "We found a positive correlation between serum CRP levels and COVID-19 severity." (PMID 35676519, 2022). "On the other hand, values of C-reactive protein, IL-6, and other biochemical factors such as lactate dehydrogenase, aspartate aminotransferase, and alanine aminotransferase exhibited high specificity against COVID-19." (PMID 35281265, 2022).
COVID-19 (continued). "Among hospitalized COVID-19 cases, higher abundance of platelets/CD34− megakaryocyte progenitors and cycling cMono was associated with oxygenation status (SaO2/FiO2, SOFA oxygenation score, ventilation status), severity (WHO ordinal), and CRP (all Pc < 0.01)." (PMID 35216673, 2022). "Omega-3 may alleviate the severity of coronavirus disease 2019 (COVID-19) by reducing the C-reactive protein (CRP) level, a marker for systemic inflammation." (PMID 36064554, 2022). "In accordance with other cohorts of hospitalized severe COVID-19 patients, both cohorts used in this study presented elevated circulating levels of C-reactive protein (CRP), fibrinogen, and D-dimer." (PMID 35937696, 2022). "Increased levels of neutrophil count, urea, AST, ALT, BILD, CK, LDH, D-dimer, CRP, PCT, Ferritin, reduced lymphocyte and monocyte count, decreased levels of albumin, and lower values of Sa02 and p02 are associated with the severity of COVID-19." (PMID 35075140, 2022). "Also, CRP has been shown to correlate with blood frequencies of the subset of extrafollicular B cells that is expanded in critically ill COVID-19 patients as well as in lupus autoimmune patients." (PMID 34744161, 2022). "During the clinical follow-up of patients with COVID-19 treated in ICUs, routine hemogram-biochemistry (C-reactive protein [CRP], ferritin, lactate dehydrogenase [LDH], and D-dimer, among others), radiography, and other examinations are performed to obtain information on the clinical course." (PMID 36060378, 2022). "In addition, COVID-19 itself increases C-reactive protein (CRP) and procalcitonin values—markers for bacterial infection, whose values are associated with disease severity." (PMID 35743662, 2022). "In addition to underlying comorbidities, excessive inflammations associated with elevated procalcitonin, C-reactive protein (CRP), D-dimer, and lactate dehydrogenase are a poor prognostic factors for patients with COVID-19." (PMID 35833737, 2022). "In this regard, certain blood biomarkers such as IL-6, ferritin, D-dimer, and CRP may be able to anticipate the development of the cytokine storm leading to COVID-19 complications." (PMID 36741367, 2022). "Early routine blood biomarkers could be key predicting factors of COVID-19 morbidity and mortality as suggested for C-reactive protein (CRP), IL-6, prothrombin and D-dimer." (PMID 35054342, 2022). "In particular, IL-6 and CRP levels might be useful to distinguish between early-stage (mild to moderate) COVID-19 patients." (PMID 36219652, 2022). "CRP apheresis starting early after patient admission, may potentially be an effective treatment COVID-19 and save lung tissue." (PMID 35407564, 2022). "Three COVID-19 patients have been treated with CRP apheresis as individual healing attempts before." (PMID 35407564, 2022). "Consequently, CRP on admission is considered a simple and independent factor that can be helpful for early detection of COVID-19 severity and thereby facilitates the guidance of treatment decisions." (PMID 35891270, 2022). "Severe COVID-19, compared to mild infection, was significantly correlated with high levels of CRP (P < 0.001) and ESR (P < 0.001) and lower levels of 25-hydroxyvitamin D (P < 0.001), LDL (P < 0.001), TG (P < 0.001), cholesterol (P < 0.001), and low real-time PCR Ct value (P = 0.018)." (PMID 36192760, 2022). "Concentrations of NLR, CRP, D-dimer, fibrinogen, ferritin, albumin, and total protein of the control group were significantly different than their counterparts in both mild-moderate and severe COVID-19 patients." (PMID 36627978, 2022). "Therefore, the generation of CRP is stimulated by inflammatory cytokines as well as by the breakdown of tissue in individuals who have COVID-19." (PMID 36431254, 2022). "Moreover, bacterial co-infections in COVID-19 patients can increase CRP levels and result in adverse clinical consequences." (PMID 36585718, 2022).